IL2 (interleukin 2)
Diseases named in the same sentence as IL2 in open-access papers (continued):
Sharing a sentence is not in itself a finding about the gene and the disease.
infection (continued). "To examine whether in vivo ZOL/IL-2-expanded Vγ2Vδ2 T cells could produce anti-TB cytokines, we employed the modified direct ICS assay without in vitro antigen stimulation so that the detected T effector cells were similar to the in vivo setting during infections." (PMID 35765887, 2022). "The vaccine lacked N and M proteins, and IFN-γ, IL2, and IFN-γ+IL2 responses to the N protein, especially Np4 that spans the N4 and N5 domains, are consistent with seroconversion to the N protein that may be derived from asymptomatic infection." (PMID 36251675, 2022). "CF mice exposed to B. pseudohinzii displayed a significant decline in IL-4, and a non-significant reduction in IL-2 serum levels, both of which serve as the predominate regulators of T-cell proliferation and B-cell activation during an adaptive immune response to infection." (PMID 34475490, 2021). "Significantly, since reduced IL-2—secreting capability of T cells is seen independent of antigen specificity; this modulation might also affect immune responses against other pathogens which a host might encounter during infection with Salmonella." (PMID 32269573, 2020). "Thus, IL-2 signals delivered early but not at later timepoints of infection when T cell effectors reach their peak, potently enhance acute IAV-induced recruitment and/or activation of inflammatory cells in the lung and transform a mild illness to a fatal infection." (PMID 31412088, 2019). "However, SeV85AB boosting resulted in a response to infection that contained a higher percentage of Ag85AB-specific poly-functional lung T cells, notably CD4+ T cells with the phenotypes IL-2+TNF-α+/IL-2+, and CD8+ T cells of phenotypes IFN-γ+IL-2+TNF-α+/IL-2+." (PMID 30123219, 2018). "Interestingly, the slopes of the lines are distinct for IL-2 (1.51) vs. IFN-γ (2.78) again emphasizing the accumulation of IFN-γ-producing CD4 T cells in the lung, relative to what is detected in the draining LN, where the CD4 T cells are elicited after infection." (PMID 29681900, 2018). "The lack of pre-infection baseline data from participants or sampling close to disease diagnosis in studies of acute infection appears to have precluded the identification of the trafficking of Tregs from the blood in response to the acute increase in cytokine concentrations, including IL-2." (PMID 28815218, 2017). "It is possible therefore that, in vivo, IL-12 may contribute to NK cell IFN-γ production when γc cytokines are lacking, such as during primary exposure (when IL-2 from antigen-specific T cells may be limiting) or later in infection when IL-15 signaling is reduced by changes in receptor expression." (PMID 27047490, 2016). "We have previously reported that the IL-2 induced lymphokine activated killing (LAK) activity of isolated CD56pos T cells is compromised in acute HCV patients who subsequently develop persistent infection but not in patients who spontaneously clear their infection." (PMID 25076408, 2014). "The idea that Treg cell inactivation contributes to the early CD4+ T cell response to infection is indirectly supported by our data showing a massive response to parasites in non-infected mice a month after JES6-1 treatment, a condition where Treg cells may have been inactivated by IL-2 deprivation." (PMID 22272258, 2012). "An observation that was consistent in DR1 and B10 mice after NC infection was that the pattern of secretion of IL-2, IFN-γ, and IL-4 was independent of epitope specificity or whether epitopes were major or minor in terms of the number of stimulated CD4 T cells." (PMID 22457834, 2012). "The absence of productive infection was further confirmed by staining for intracellular p24 expression where we found that CCL19-treated infected CD4+ T-cells resulted in <1% p24-positive cells in contrast to IL-2/PHA activated infected CD4+ T-cells (mean p24 expression ~6-9%; n = 2)." (PMID 21992606, 2011).
infection (continued). "Serum levels of IL-10, IL-2, IL-6, IL-8, and TNF-α were analyzed and compared between patients with and without HAdV-36 infection." (PMID 40284995, 2025). "In this context, the present study aims to compare IL-10, IL-2, IL-6, IL-8, and TNF-α levels between patients with and without HAdV-36 infection." (PMID 40284995, 2025). "Unlike Il2-null cells, however, Srf-null memory CD8+ T cells do not persist following primary infection." (PMID 39261466, 2024). "Compared to mice without pre- and post-infection, the A2l19f RSV-infected group exhibited higher IL-2+ expression in both CD4+ and CD8+ cell populations with peptide stimulation." (PMID 38629077, 2024). "At the IL-2 promoter, methylation levels decreased in 3 of 4 animals post-SIV infection compared with pre-infection, although this difference was not significant (p = 0.1133) likely because methylation levels remained unchanged in 1 of 4 animals." (PMID 39772149, 2024). "Neither risks for infections nor rejections were significantly increased when applying thecutoffs separately in the ATG and IL-2 RA group." (PMID 39606231, 2024). "Almost all vaccinated participants with no prior infection exhibited IFN-γ, IL-2 and IFN-γ+IL2 responses to S glycoprotein subpools (89%, 93% and 27%, respectively) mainly directed to the S2 subunit and were more robust than responses to the N or M subpools." (PMID 36251675, 2022). "Here we found that increased plasma concentrations of IL-10, MCP-1, IL-1rα, IL-2, IL-6 and SCGFβ had a negative impact on CD4:CD8 ratio during acute infection (< 180 days post infection), as evaluated by linear regression model." (PMID 35165387, 2022). "More recently, in a randomized, double-blind, placebo-controlled trial of Ld-IL2 therapy in SLE, no serious infection was observed in the IL-2 group, in contrast to two cases in the placebo group, again supporting this notion." (PMID 34618873, 2021). "Plasma levels of six cytokines (IL-2, IL-3, IL-4, IL-7 and VEGF) were not significantly altered by Kp-1705 infection nor were they affected by MTD12813 treatment." (PMID 34873199, 2021). "We observed that the deletion of the cryptococcal VLP1 gene did not affect the production of cytokines such as IL-2, INF-γ, Il-17A, and IL-18 in host blood in the early, middle, and late stages of infection." (PMID 34072011, 2021). "For having remained below the technique detection limit, we did not interpret the following values: uninfected mice, IL-2, IL-4, IL-10, and IL-17 values of infected mice, as well as IFN-γ, TNF-α, and IL-6 levels at the infection times from 6 to 240 h." (PMID 34660334, 2021). "At both early and late stage of the infection, antigen presentation of rFhCB3 and rFhCL2 resulted in higher stimulation index of CD4+ T cells which was IL-2 mediated, although no statistically significant when compared to uninfected animals." (PMID 34215335, 2021). "PDGFRβ correlated negatively in BSIII–IV and positively in BSV–VI with several cytokines (IL-10, IL-12, IL-13, IL-2, IL-4 and TNF-α) but only in the absence of infection." (PMID 33723589, 2021). "In line with this in our study, Type-1 (IFN-γ, TNF-α, and IL-2)- and Type-17 (IL-17A)- cytokines were significantly decreased in INF individuals when compared to those without Ss infection." (PMID 33042134, 2020). "The levels of IFN-γ, TNF-α and IL-1β, but not IL-2, at MGAS5005, MGAS315, and MGAS6180 infection sites were higher in SseM1-immunized mice than in control mice." (PMID 32308652, 2020). "However, unlike WT mice, infection with Salmonella did not reduce the ability of activated T cells from these mice to produce IL-2, suggesting that NO produced by infected splenic CD11b+Gr1+ cells were responsible for downregulating IL-2 production from activated T cells." (PMID 32269573, 2020).
infection (continued). "Similar to WT mice, in the CNS of Rag1−/− mice IFN-α1, IFN-β, TNF, IL-1α, IL-1β, IL-6, and IFN-γ mRNA levels increased following i.c. infection with ZIKV, and IL-2, IL-3, IL-4, and IL-5 mRNA was not detectable (data not shown)." (PMID 31511023, 2019). "Taken together, IFN-γ+ TEM cells, and especially IL-2+ TCM cells and their distribution are more effective biomarkers to assess vaccine-induced protection, regardless of models of primary infection and late persistent infection." (PMID 30425711, 2018). "During murine CMV (MCMV) infection, CD4+ Tcells maintain inflationary virus-specific CD8+ T-cell responses via IL-2 but not IL-21." (PMID 30279090, 2018). "When activated by a second round of infection, the TEM cells release pro-inflammatory cytokines, most notably TNF-α, TGF-β, and IL-2." (PMID 29783736, 2018). "In presence of IL-2 and IL-15 there was a significant increase in MIP-1α levels and RANTES had near significance (P = 0.0512) at 12 h post-infection (p.i.)(data not shown)." (PMID 30405602, 2018). "It was observed that rTgHSP70 immunization did not alter the production of IL-2, IL-4, IL-6, IL-10, IL-17a, IFN-γ, nor TNF, although infection with T. gondii promotes the production of inflammatory cytokines IL-6, IFN-γ, and TNF in all groups of mice." (PMID 28487847, 2017). "Total CD4+ T cells were purified from animals pre-infection and cultured for 24 h at 37 °C in CO2 incubator with or without IL-2 treatment, and the exosomes were isolated, quantified and kept in −70 °C for use." (PMID 29142313, 2017). "Early upon infection, vaccinates exhibited higher numbers of antigen-specific IFN-γ/TNF-α/IL-2 Tcm cells than did non-vaccinates, and such dissimilar responses between vaccinates and non-vaccinates early after challenge is associated with disease outcome." (PMID 27799930, 2016). "Early after challenge (3 weeks post-infection), non-vaccinates had greater antigen-specific interferon-γ (IFN-γ)/tumor necrosis factor-α (TNF-α) and lesser IFN-γ/TNF-α/IL-2 responses by Tcm cells than did vaccinated animals." (PMID 27799930, 2016). "At 4 and 9 weeks post-challenge, increased levels of triple-positive CD4+ T cells (co-expressing IFN-γ, TNF-α and IL-2), but not CD8+ T cells, were observed in the spleens and lungs of the Rv3628-immunized group compared with the infection control group." (PMID 27097115, 2016). "Moreover, the increase of CD25 membrane expression seen after infection may imply that cells with higher CD25 levels, in an environment poor in cytokines critical for their differentiation, can keep a relative efficiency for the IL-2- or IL-15-dependent signaling pathways." (PMID 26745276, 2016). "The 4-1BB-mediated upregulated expression and secretion of IL-2 and IFN-γ play a decisive role in the generation of effector immune responses and eventual homeostasis with a net outcome of clearance of infection in the absence of a collateral damage." (PMID 27049955, 2016). "Most infections were carried out in the presence of PHA and IL-2 stimulation, although stimulation with anti-CD3, anti-CD28 mabs resulted in similar levels of infection (not shown)." (PMID 26055104, 2015). "Hence, the treatment approaches might include targeting proviral infection using the activation of Vγ9Vδ2 T cells with aminobisphosphonates and IL-2 to improve the anti-viral activity but not on the prolonged virus as the viral load is severe in this condition." (PMID 25426120, 2014). "As the downstream targets of NF‐κB activation, we found that inflammatory cytokines IL‐2, IL‐4, IL‐6, TNF‐α, and IFN‐γ were significantly increased in the infected organoids compared to the organoids without any infection." (PMID 25214524, 2014). "For this purpose, PBMCs were harvested from healthy donors and the non-adherent subpopulation was activated with IL2 and PHA for 48 hours and then IL2 alone for 24 hours before infection with HIV-1 BaL." (PMID 24404168, 2014).
infection (continued). "In conclusion, induction of a balanced Th1/Th17 response and production of key effector cytokines, such as IFNG, IL2, IL17, IL21, IL22 and IL23A was observed in animals that controlled infection, regardless of previous BCG-vaccination." (PMID 24505407, 2014). "However, Gö6850 could not reliably inhibit productive infection driven by IL-2." (PMID 23201205, 2013). "An increase was observed in the frequency of pSTAT5+ CD4 T cells that responded to ex vivo IL-2 stimulation regardless of infection, indicating that neutrophils suppress CD4 T cell responsiveness to IL-2." (PMID 23754944, 2013). "Using this information in the current study, we demonstrate that the pattern of secretion of IL-2, IFN-γ, and IL-4 by CD4 T cells activated by NC infection is largely independent of epitope specificity and the magnitude of the epitope-specific response." (PMID 22457834, 2012). "More particularly ELISA assays indicate that Treg cell cytokine pattern (IL-2, IFN-γ, TGFβ and IL-10) remains unchanged after 48 h of infection (data not shown)." (PMID 22359669, 2012). "The sub-dominant epitopes not only failed to elicit IFN-γ and in vivo cytotoxicity during infection, but they also did not stimulate TNF-α, IL-2 or IL-10 secretion by CD8+ T cells." (PMID 21779365, 2011). "After the first session of TPE+CVVDH, a negative correlation trend was found between IFN-γ, IL-2, IL-12 (p70), TNF-α, and parasite density, which may be due to the complex biological mechanisms triggered by infection with P. falciparum." (PMID 41552719, 2025). "We measured Type 1 (IFN-γ, TNF-α, IL-2), Type 17 (IL-17, IL-22), and proinflammatory cytokines (IL-1α, IL-1β) in QuantiFERON (QFT) supernatants from TBI individuals with (TBI+Hel+) and without (TBI+Hel−) infection." (PMID 41583474, 2025). "IL-2 is primarily produced by activated CD4+ and CD8+ T cells and this data suggests a higher level of T cell activation in the spleens of non-survivors early after infection." (PMID 39513496, 2024). "Importantly, this IL-2 induction did not persist after day 3, possibly allowing for heightened IFN-γ production during the early stages of infection in the dose B-treated group." (PMID 38283346, 2023). "Therefore, we monitored the levels of IL-6, IFN-γ, IL-2, IL-10, TGF-β, TNF-α, IL-12, and IL-17 in the lung lysates of M. tb-infected mice with and without L-GSH treatment at varying stages of the infection to assess the granulomatous response." (PMID 35453358, 2022). "Using the clonal population of GP33–41/Db-specific Il2ramut/mut and WT P14 TCR transgenic memory CD8+ T cells primed upon Lm-GP33–41 infection, we further confirmed that P14 memory CD8+ T cells also failed to competitively expand when IL-2 signals were impaired." (PMID 35474218, 2022). "Among subjects receiving SARS-CoV2 vaccine injection, fewer CD8+ T cells producing interferon alpha and TNF-αwere found in the subjects without previous infection, and CD4+ cells with interleukin 2 expression were enriched as the major immune cells after vaccine injection." (PMID 36146454, 2022). "The levels of IL-2, IL-4, IL10, and IL-17 were also not significantly altered by infection." (PMID 33815321, 2021). "Moreover, the plasma levels of IL-2, IL-6, IL-8, IL-10, and TNF-α, observed in severe infection, are prominently greater than those with nonsevere infection." (PMID 34844296, 2021). "Furthermore, increased numbers of NKT cells recruited to the lungs in response to hRSV- but not hMPV-infection was detected, resulting in a reduction in the expression of IFN-γ and IL-2 by these cells." (PMID 32463330, 2020). "IL-2 production after DC stimulation with the H3.3K27M peptide was greatly stimulated by adding phorbol ester (TPA) to the culture; in contrast, RIPO(H3.3) infection yielded similar levels of J76CD8+TCR+ activation without TPA." (PMID 31988324, 2020).
infection (continued). "Moreover, the plasma levels of IL-2, IL-6, IL-8, IL-10, and TNF-α, observed in severe infection, are prominently greater than those in nonsevere infection." (PMID 32299202, 2020). "In addition, we did not observe any secretion of IL-2, IL-10, IL-13, and IL-6 during an AIC infection." (PMID 31801841, 2019). "Moreover, it was shown that the antigen-specific IL-2+CD4+ T cell subsets were negative for KLRG1, which is a surface marker of terminally differentiated T cells, during Mtb challenge infection." (PMID 30123219, 2018). "Multiparameter flow cytometry confirmed that polyfunctional T. cruzi-responsive T cells in SD subjects are enriched in highly competent IL-2-producing T. cruzi-specific CD4+ T cells, consistent with exposure to T. cruzi but the absence of a long-term active infection." (PMID 28966620, 2017). "Importantly, both IFN-γ/TNF-α/IL-2 and IFN-γ/TNF-α responses to infection at 3 WPI (data not shown) and 8 WPI exceeded (P < 0.05) respective responses to vaccination upon recall stimulation of long-term cultures with Ag85A/TB10.4." (PMID 27799930, 2016). "In the comparative analysis between the Leishmania species identified in this study, higher concentration of IL-2 and IFN-γ in the sera of patients with primary infection, compared to sera from noninfected or those with secondary Leishmania infection, was observed." (PMID 25295285, 2014). "Interestingly, at six weeks post infection in the lungs, there was also a negative correlation between IFN-γ+TNF-α+IL-2+ and IFN-γ+TNF-α+ CD4 T cells and bacteria levels." (PMID 23977248, 2013). "Taken together, our data showed that the adjuvanted subunit and MVA strategies led to different T cell subset combinations pre and post infection and that TNF-α/IL-2 double producing but not IFN-γ single producing CD4 T cell subsets correlated with protection in the mouse TB model." (PMID 23977248, 2013). "Thus, there was a strong negative correlation between the amount of TNF-α+IL-2+ CD4 T cells induced by the vaccines and the level of bacteria in the lungs 6 weeks after infection (R2 = 0.93 and 0.75, and p<0.0001 for Ag85B and TB10.4, respectively)." (PMID 23977248, 2013). "Indeed, over the course of an infection, not all CD8 T cells produce IL-2 and it was found that IL-2 producing-CD8 T cells are more prone to differentiate into memory cells while T cells that do not produce IL-2 instead gain effector cell traits." (PMID 38510150, 2024). "Notably, during primary infection of the chimera mice, some epitopes (Ova257–264, gB498–505) but not others (GP33–41) required IL-2 signals for optimal expansion, whether expressed in Lm or by other microbial pathogens (VSV, HSV-2)." (PMID 35474218, 2022). "Furthermore, the levels of interleukin (IL)-2, IL-4, IL-6, IL-22, and interferon (IFN)-γ, but not that of tumor necrosis factor alpha (TNF-α), IL-10, and IL-9, increased to their highest levels at day 4 post-infection and decreased thereafter." (PMID 31711531, 2019). "IL-18 is believed to be directly involved in anti-infection and antitumour immunity and exerts negative feedback on IL-1β expression; on the other hand, IL-1β mainly induces inflammation injury by promoting the secretion of IFN-γ, IL-2 and GM-CSF by NK cells and T cells." (PMID 31827916, 2019). "As the infection protocol requires culturing cells in IL-2-containing media, which can upregulate aNKR ligands, we cultured unCD4 T cells under the same conditions as an internal control to observe the effects of HIV infection on aNKR profiles irrespective of the effects of IL-2." (PMID 29023371, 2017). "In humans, preexisting IFN-γ+ CD8+ T cells lacking IL-2 production, and not IFN-γ+ IL-2+ CD8+ T cells, could be correlated with decreased symptom scores upon natural infection with pandemic H1N1 influenza virus, arguing against the necessity of CD8-derived IL-2 for clinical protection." (PMID 27512056, 2016).